PXN (paxillin)
Diseases named in the same sentence as PXN in open-access papers (continued):
Sharing a sentence is not in itself a finding about the gene and the disease.
cancer (continued). "We also found that FAK levels are reduced in cancer cells in vivo compared with cell culture systems and that disrupting a key site for FAK phosphorylation on Paxillin leads to enhanced cancer cell migration in vivo." (PMID 36723624, 2023). "Consequently, paxillin may be a promising target for cancer therapy and prognosis in the future." (PMID 37175948, 2023). "This antagonistic coupling of NF-κB and PTEN controls the expression of many downstream effectors that drive cancer cell invasion and metastasis including F-Box and WD40 Domain Protein 7 (FBW7), RhoGDIα and paxillin." (PMID 37853467, 2023). "Lut combined with AsA treatment downregulated PI3K/AKT signaling (PI3K, AKT and p70S6K), JNK/p38 MAPK signaling and FAK signaling (integrin β1, paxillin and FAK) and upregulated ERK signaling to induce apoptosis and inhibit cancer cell migration." (PMID 36672499, 2023). "By contrast, the overexpression of MCAK is associated with an increased MT catastrophe rate, which stabilizes and enlarges FAs with elevated paxillin, FAK and p-FAK content in cancer cells." (PMID 34830827, 2021). "Accordingly, immunofluorescent staining of paxillin and F-actin demonstrated abnormally enhanced focal adhesions in PAX8-depleted cancer cells." (PMID 31050342, 2019). "Higher cytoplasmic LIF enhances cancer vascular dissemination and local invasion mechanistically through modulation of YAP1-FAK/PXN signaling." (PMID 30504771, 2018). "Among these pathways are some key pathways that regulate cancer progression, including the PI3K/AKT, STAT3, MEK/ERK, JNK, FAK, Paxillin, and p130cas pathways." (PMID 29132432, 2017). "Src inhibitors reduce the migration of several types of human cancer cell through blocking Src, FAK, p130CAS, and paxillin activation." (PMID 29234409, 2017). "Importantly, paxillin δ is able to suppress full-length (α)-paxillin signaling as well as interactions with actin-binding and integrin-linked proteins due to the lack of LD1 domain, thus suggesting a potential role in suppressing the migratory phenotype of cancer cells." (PMID 28214467, 2017). "FAK is known to interact with many proteins such as Paxillin, Src, EGFR, Her-2, MET, PI3K, VEGFR-3 and the scaffolding function of FAK plays an important role in cancer cell signaling." (PMID 26980710, 2016). "In human cancers, miR-137 can modulate the expression of a multitude of genes, including EZH2, FMNL2, and Paxillin." (PMID 24970808, 2014). "The inhibitory effect of CX-4945 on the TGF-β1-induced invasion of A549 cells was further confirmed by evaluating the activation of the cancer invasion-related molecules FAK, Src, and paxillin." (PMID 24023938, 2013). "In vitro studies with PFOA exposure in a uterine cell line showed that PFOA treatment promoted invasion and migration of cancer cells mediated through activation of ERK/mTOR signaling, which cross talks to the MAPK pathway, another potential upstream mediator of paxillin." (PMID 38535903, 2024). "Adherens junction, focal adhesion, pathways in cancer, VEGF signaling pathway, tight junction, ECM receptor interaction, B cell receptor signaling pathway, and JAK STAT signaling pathway were mainly enriched in the high PXN expression group." (PMID 36923874, 2023). "Co-expressed genes (PXN, ITGA3, TES, and MET) were identified and analyzed by FunRich with CAV1 and CAV2, revealing a significant correlation with focal adhesion (p < 0.001), which has a vital influence on cancer progression." (PMID 36830672, 2023). "In addition to this classical neurotrophic molecule, we demonstrated that CCL2 derived from DRG neurons activates the cancer cell cytoskeleton through the CCR4 receptor and the entailing paxillin phosphorylation." (PMID 37607005, 2023). "In this regard, phosphorylation of paxillin at tyrosine residues 31 (Tyr-31) and 118 (Tyr-118) by the nonreceptor protein tyrosine kinase SRC and focal adhesion kinase 1 (FAK1) is essential for cytoskeleton assembly and cancer cell migration." (PMID 37607005, 2023).
cancer (continued). "Moreover, the reorganization of the actin network is required for cancer cell invasion and metastasis, and this process is regulated by various proteins, such as FAK, Src, and paxillin, the most common signaling components in F-actin reorganization." (PMID 37175948, 2023). "Moreover, the JNK pathway activates migration by inducing the phosphorylation of paxillin, which is an adaptor protein related to FAK activation in different cancer cells." (PMID 33800291, 2021). "Our data revealed that AC-93253 iodide significantly represses FAK, JNK, Paxillin, and p130cas phosphorylation or protein expression in PC9, PC9/gef, and A549 cells, which may lead to cancer cell invasion and migration inhibition." (PMID 29132432, 2017). "Paxillin, GIT1, and p190RhoGAP are key regulators of focal adhesion turnover and invadosome formation, all of which are crucial for the motility and invasiveness of cancer cells." (PMID 26857455, 2016). "The authors also found that PAK1-induced cancer metastasis may involve activation of c-Jun NH2-terminal kinase (JNK) and phosphorylation of paxillin." (PMID 25182632, 2014). "The level of PXN mRNA was increased in 27 of 30 (P < 0.001) cancer tissues in comparison with that of nontumorous tissues." (PMID 24180516, 2013). "The expression of fascin-1 was greater in T1+T2 than T3+T4 cancer (mean rank 119.70 vs. 100.50, P = 0.007), as was that of ezrin (mean rank 102.29 vs. 117.20, P = 0.047) but not paxillin." (PMID 23209815, 2012). "Hence, it can be assumed that PXN plays more role in cellular migration and invasion, as observed in carcinoma, rather than the local invasion." (PMID 38962075, 2024). "Taken together, these results, in agreement with our in vitro observations, suggest that the CCL2-CCR4 pathway affects paxillin phosphorylation in cancer cells and the proximity of the cancer to neural cells, even in the absence of perineural lining of cancer cells." (PMID 37607005, 2023). "Since HPIP has been reported to be an activator of focal adhesion kinase (FAK) to regulate cell adhesion and migration, and phosphorylation of FAK (Tyr397) and Paxillin (Ser178) promote cancer cell migration and invasion, we investigated whether TXX-1-10 regulates FAK and Paxillin." (PMID 34326318, 2021). "The expression of the 3 proteins was higher with N+ than N0 cancer (P≤0.006) and was higher with stages III+IV than stages I+II cancer (mean rank for fascin-1, 118.95 vs. 97.25, P = 0.002; ezrin 116.68 vs. 99.69, P = 0.022; paxillin: 117.09 vs. 99.25, P = 0.010)." (PMID 23209815, 2012). "However, no studies have analyzed PXN from a pan-cancer perspective." (PMID 34135128, 2021).
infection (20 papers, 2013 to 2025). The state of being infected such as from the introduction of a foreign agent such as serum, vaccine, antigenic substance or organism. "In LAD, mutations in integrin β2 disrupt its interaction with paxillin, impairing leukocyte adhesion to the endothelium and preventing effective migration to sites of infection or inflammation." (PMID 40001476, 2025). "Both E6 from bovine papillomavirus (BE6) and E6 from the high-risk HPV-16 strain interact with the LD motifs of paxillin during infection, as indicated by yeast two-hybrid and immunoprecipitation studies." (PMID 33572997, 2021). "Given the mechanosensitivity of talin and paxillinand their participation in cardiac mechanotransduction, we evaluated the expression anddistribution of talin/paxillin and proteins associated during infection of cardiac cellsby T. cruzi." (PMID 31433004, 2019). "Our data demonstrate that both mechanosensitive proteins, talinand paxillin, exhibited reduced expression levels after 72 h of infection along withmassive loss of immunoreactivity in highly infected cells." (PMID 31433004, 2019). "Talin and paxillin spatial distribution in T.cruzi-infected cardiomyocytes in vitro werealtered associated with a downregulation of these proteins and mRNAs levelsat 72 h post-infection (hpi)." (PMID 31433004, 2019). "This dysfunction leads to recurrent infections and poor wound healing, highlighting the importance of paxillin in immune responses." (PMID 40001476, 2025). "C. jejuni (SI) was associated with increased localization of bacterial clumps with integrin effector paxillin (green) early in infection (1 hpi)." (PMID 40471665, 2025). "Invading O. tsutsugamushi colocalizes with integrin α5β1 and activates integrin signaling effectors, including focal adhesion kinase, Src kinase, and RhoA GTPase, as well as signaling adaptors, such as talin and paxillin, to the site of infection." (PMID 36541760, 2023). "To investigate adhesion complex formation in hDCs and the potential role of this complex in migration induced by L. infantum, we analyzed pFAK and p-paxillin expression in the context of infection by L. amazonensis, L. braziliensis and L. infantum." (PMID 34207943, 2021). "This is further supported by our observation that paxillin localization changes from the cytosol to the focal adhesion during infection." (PMID 34425711, 2021). "COS7 cells were infected, and 24 h post-infection (hpi), cells were fixed and prepared for indirect immunofluorescence imaging of paxillin-positive FAs." (PMID 32843479, 2020). "We found that infection enhanced interaction between FAK and integrin β1, which inhibits the phosphorylation of FAK and subsequently deactivates paxillin, thereby causing FA accumulation." (PMID 30700983, 2018). "After infection, paxillin was moderately, but significantly dephosphorylated for the infected vehicle control, as expected, and the 150 μM concentration of the inhibitor (p<0.5)." (PMID 26556238, 2015). "Studies have shown that angiotension-II-induced focal adhesion formation is inhibited by infection with Adeno-PDK1-Y9F via paxillin." (PMID 26684827, 2015). "We observe moderate, but significant dephosphorylation of paxillin as early as 2 hours post-infection." (PMID 26556238, 2015). "Similar to our in vitro findings, mice pre-treated with AKB-4924 showed less paxillin degradation compared to mock treated animals after UPEC CFT073 infection." (PMID 25927232, 2015). "The virus activates EGFR when it infects monocytes, and employs integrins and paxillin at the beginning of infection." (PMID 26147640, 2015). "During early-stage infection, C. jejuni (SI) could be observed clustering to paxillin-rich membrane structures when adhering to the HT29 cells." (PMID 40471665, 2025).
infection (continued). "Conversely, the most significantly downregulated proteins, including PXN (p = 0.0127) and CELA2A (p = 0.0469), were linked to cell adhesion, migration, and metabolic regulation, suggesting a decline in cellular activity and metabolic demand during infection." (PMID 40429216, 2025). "Interestingly, it was reported that paxillin phosphorylation is downregulated during late infection." (PMID 33572997, 2021). "Interestingly, our network analysis also identified a potential new role for miRNA-342 in cytoskeleton regulation (PFN1, PXN) during infection." (PMID 30619110, 2018). "Together, these observations imply that members of the Src family, possibly other than c-Src, may play a role in C. parvum infectivity, and that paxillin may also be a factor in infection." (PMID 26556238, 2015). "The lack of co-localization suggests that paxillin may not directly interact with C. parvum, but these observations suggest that moderate dephosphorylation of paxillin may play a role in the continued infection process of the parasite." (PMID 26556238, 2015). "However, we did see a moderate, but statistically significant (p<0.05), dephosphorylation of paxillin, at the Tyr118 residue, as early as 2 h post-infection." (PMID 26556238, 2015). "Furthermore, we show that SHP-2 may affect the phosphorylation status of paxillin, a focal adhesion protein, during the infection process." (PMID 26556238, 2015). "Additionally, the entry efficiency of these viruses (with and without the UL128-131 complex) was unchanged during infection of wild type or paxillin-deficient fibroblasts, strongly suggesting contrasting mechanisms of entry into monocytes vs. fibroblasts." (PMID 23853586, 2013). "Since repositioning of FAK and paxillin away from the signaling layer may prevent crucial interactions and events necessary for FA disassembly, these results indicate a possible mechanism for the observed increase in FA maturity and resistance to blebbistatin during infection." (PMID 33572997, 2021). "Infection of E. coli O157:H7 inactivated focal adhesion kinase (FAK) and paxillin, increased focal adhesion (FA) and actin polymerization, and decreased cell migration in Caco-2 cells, which were rescued by integrin β1 antibody blocking or knockout." (PMID 30700983, 2018). "In FHs 74 Int cells infected with C. parvum, SHP-2 expression was upregulated for up to 4 hours post infection which resulted in a modest dephosphorylation of the SHP-2 substrate, paxillin." (PMID 26556238, 2015). "However, the phosphorylation levels of vimentin, vinculin, paxillin, and LIM domain kinase 1 were upregulated at 6 h and 36 h after infection." (PMID 38759153, 2024). "At the earliest infection time (24 hpi) talin and paxillin presented no changes intheir expression and distribution pattern." (PMID 31433004, 2019). "Furthermore, we show that one potential target that SHP-2 acts upon is the focal adhesion protein, paxillin, which undergoes moderate dephosphorylation following infection, with inhibition of SHP-2 rescuing paxillin phosphorylation." (PMID 26556238, 2015). "Previous studies have identified several cellular proteins that may function at early steps of infection, including platelet-derived growth factor receptor-α (PDGFR-α), epidermal growth factor receptor (EGFR), DC-SIGN, αVβ3 and β1 integrins, and paxillin." (PMID 26147640, 2015). "Therefore, in contrast to that observed for SHP-2, paxillin did not localize with the sporozoite infection site." (PMID 26556238, 2015). "Furthermore, our studies reveal that the presence of the gH/gL/UL128-131 complex on the viral envelope, through its activation of the integrin/Src/paxillin pathway, is necessary for efficient HCMV internalization into monocytes and productive infection in monocyte-derived macrophages." (PMID 23853586, 2013).
infection (continued). "We found that the expression of paxillin did not influence either BADwt or BADrUL131 entry into fibroblasts, suggesting that although BADwt triggers paxillin phosphorylation during infection of fibroblasts, paxillin regulation is not required for efficient viral internalization into this cell type." (PMID 23853586, 2013). "Infection with Δeae strain did not suppress FAK and paxillin, indicating a regulatory role of intimin in host signaling transduction." (PMID 30700983, 2018).
adenocarcinoma (3 papers, 2014 to 2024). A common cancer characterized by the presence of malignant glandular cells. "Conversely, adenocarcinoma cells (MDA-MB-231) exhibit a distinctive response: they respond to stiffening transitions displaying unvaried paxillin levels at FAs sites, indicative of altered mechanosensing-related structures." (PMID 38903185, 2024).
colorectal (2 papers, 2021 to 2023). "At the same time, phosphorylation-Akt is the downstream substrate of pY88-paxillin, so knocking out the expression of PTPRT can phosphorylate paxillin tyrosine-88 residue to activate the PI3K/AKT pathway to promote colorectal carcinogenesis." (PMID 37175948, 2023).
neurodegenerative disease (1 paper, 2012). A disorder of the central nervous system characterized by gradual and progressive loss of neural tissue and neurologic function. "In addition, some CAMs have been shown to shuttle between FA and nucleus to regulate gene expression, including CDK5, ERK, GSK3B and COPS5 (JAB1) and members of the LIM family of proteins (PXN and Trip6), many of which have been implicated in the molecular pathology of neurodegenerative diseases." (PMID 22815752, 2012).
PXN also shares sentences with these, for which no sentence is quoted: chronic myeloid leukaemia (2 papers); gastric adenocarcinoma (2); malignant salivary gland tumor (2); thyroid cancer (2); adenoid cystic carcinoma (1); adenomatoid odontogenic tumor (1); adenosquamous carcinoma (1); Alzheimer disease (1); Anxiety (1); astrocytomas (1); benign salivary gland tumor (1); cardiac hypertrophy (1); cholangiocarcinoma (1); co-infection (1); colon adenocarcinoma (1); colorectal adenocarcinoma (1); corneal diseases (1); coronary artery disease (1); diabetes (1); dilated cardiomyopathy (1); dysplasia (1); Epithelial Dysplasia (1); erectile dysfunction (1); fibrosis (1); heart disease (1); Hyperkeratosis (1); hypertrophic cardiomyopathy (1); idiopathic pulmonary arterial hypertension (1); infectious disease (1); leukemia (1).
A further 27 diseases each share a sentence with PXN in 1 paper.